FABP4 (fatty acid binding protein 4)
Diseases named in the same sentence as FABP4 in open-access papers (continued):
Sharing a sentence is not in itself a finding about the gene and the disease.
breast cancer (continued). "In addition, another large retrospective study reported that statin use was associated with a significant reduction in deaths from breast cancer (aHR = 0.60) and, most importantly, statins were found to suppress the expression of FABP4 by previous basic research." (PMID 26959740, 2016). "This is achieved by recruiting the SWI/SNF complex and HDAC1 to transcriptionally repress CD36 and FABP4 expression in breast cancer cells." (PMID 40002245, 2025). "Unpublished data from our group show that OB EVs are enriched in palmitic acid and fatty acid binding protein 4 (FABP4), a molecule known to promote breast cancer progression through the IL-6/STAT3/ALDH1 pathway." (PMID 40485730, 2025). "This transcription factor binds to SREBP1 promoting its expression and the subsequent increase in FABP4 (fatty acid binding protein 4), leading to breast cancer cell proliferation." (PMID 40427160, 2025). "Altogether, study results point to the role of FABP4 in breast cancer progression and should be further evaluated as a prognostic biomarker in breast cancer with a dysfunctional or reduced amount of BRCA1 protein." (PMID 40870889, 2025). "For example, how FABP7 regulates the metabolic phenotype of GBM stem cells and how FABP4 affects the maintenance of breast cancer stem cells." (PMID 40717587, 2025). "Research indicates that FABP4 is often upregulated in breast cancer tissues, promoting aggressive phenotypes." (PMID 40870889, 2025). "Only one study has shown CD36 as a direct binding partner of FABP4, facilitating fatty acid transfer from adipocytes to breast cancer cells." (PMID 41392988, 2025). "In the tumor-adipose microenvironment, FABP4 is highly expressed and drives breast cancer progression through metabolic reprogramming, immune suppression, and metastatic adaptation." (PMID 40717587, 2025). "In this study, we collected surgical breast tissue samples from 96 women with different subtypes of breast cancer and comprehensively analyzed the expression pattens of FABP4 and FABP5." (PMID 40106183, 2025). "We found that distinct expression profiles of FABP4 and FABP5 were associated with their unique roles in breast cancer development." (PMID 40106183, 2025). "In summary, while FABP4 and FABP5 play distinct roles in regulating lipid availability for tumor cells, both are associated with poor prognoses in breast cancer." (PMID 40106183, 2025). "In fact, fatty acid-binding protein 4 (FABP4) was shown to be involved in the high-fat-diet-induced generation of ROS during tumorigenesis of a mammary tumor, whereas FABP5 was suggested to be involved in the metastasis of MM." (PMID 39940783, 2025). "Recent studies of FABP4 protein in breast cancer tissues suggest elevated levels of FABP4 as poor prognostic markers for breast cancer." (PMID 40870889, 2025). "We further assessed FABP4 expression across different breast cancer subtypes, including hormone sensitive (ER + /PR + /HER2-), HER2 positive (ER-/PR-/HER2 +), and triple negative (ER-/PR-/HER2-)." (PMID 40106183, 2025). "To investigate the role of FABP4 in breast cancer development and progression, we collected surgical breast cancer tissues from 96 women diagnosed with various subtypes of breast cancer and analyzed FABP expression patterns in these samples." (PMID 40106183, 2025). "Conversely, downregulation of SCD1 and FABP4 expression significantly inhibits lipid transport in the cancer tissue microenvironment, induces ferroptosis, and reduces breast cancer recurrence and metastasis." (PMID 39664391, 2024). "Herein, we report the generation of humanized monoclonal antibodies blocking FABP4 activity for breast cancer treatment in mouse models." (PMID 39054536, 2024).
breast cancer (continued). "Secondly, TAMs with lipid accumulation facilitate breast cancer progression through the FABP4-dependent lipolysis and lipid utilization pathways." (PMID 39513934, 2024). "FABP4 is a biomarker for metabolic diseases and has been shown to promote proliferation, resistance, and metastasis in ovarian cancer, breast cancer, and prostate cancer." (PMID 39402324, 2024). "We identified one clone, 12G2, which was able to effectively block FABP4 activity and inhibit mammary tumor growth in different mouse models." (PMID 39054536, 2024). "A reduction in lipid proteins, including fatty acid binding protein 4, which regulates inflammatory and metabolic processes in adipocytes and TAMs, led to reduced metastasis and enhanced sensitivity to chemotherapy in breast cancer xenografts." (PMID 39273252, 2024). "(E) Transwell measurement of migration of breast cancer cells cocultured with FA- or BSA-treated FABP4 WT or KO macrophages (Mφ)." (PMID 39513934, 2024). "By analyzing FABP4 expression in TAMs with human breast cancer specimens, we found that FABP4 expression in TAMs, especially CD163+ TAMs, correlated directly with tumor size, grade, metastasis and even patient survival." (PMID 39513934, 2024). "In summary, we identified FABP4 as a new adipokine promoting breast cancer development and developed the first humanized anti-FABP4 monoclonal antibodies for treating breast cancer in mouse models." (PMID 39054536, 2024). "One clone, named 12G2, which significantly reduced circulating levels of FABP4 and inhibited mammary tumor growth, was selected for further characterization." (PMID 39054536, 2024). "Using E0771 mammary tumor cells, we confirmed the essential role of FABP4 in mediating LA-induced tumor migration effect in macrophages." (PMID 39513934, 2024). "Humanized V9 monoclonal antibody targeting FABP4 can inhibit tumor growth and metastasis in breast cancer." (PMID 39125923, 2024). "Stearoyl-CoA desaturase-1 (SCD1) in breast cancer cells can synergistically protect tumor cells with fatty acid binding protein-4 (FABP4) in the tumor microenvironment, shielding them from oxidative stress-induced ferroptosis." (PMID 39664391, 2024). "In the syngeneic Lewis lung carcinoma (LLC) mouse tumor model and mouse xenograft model using MDA-MB-231 breast cancer cells, FABP4 expression was upregulated by hypoxia and re-oxygenation in adipocytes and tumor endothelial cells but not in cancer cells." (PMID 38060103, 2023). "In this experiment, CM from breast cancer cell lines suppressed PPARγ and its target genes FABP4 and CD36 in both ECs and pericytes compared to CM from HMECs." (PMID 37816052, 2023). "A link between FABP4 and lipolysis in the survival and growth of cancer cells through adipocytes has also been reported in breast cancer tissues." (PMID 38060103, 2023). "It was demonstrated that CAAs surrounding breast cancer are smaller and exhibit lower lipid content, reduced levels of adipocyte markers (leptin, adiponectin, resistin, FABP4), and overexpression of proinflammatory cytokines and matrix-remodeling proteins." (PMID 37481560, 2023). "This study explored the potential targets of RGZ as antiangiogenic agents in breast cancer therapy and highlighted FABP4, ADIPOQ, PPARG, PPARGC1A, CD36, and CREBBP as potential targets of RGZ." (PMID 36114448, 2022). "Nur77 recruits SWI/SNF complex and HDAC1 to suppress the transcription of CD36 and FABP4, hampering breast cancer cells uptake of exogenous FAs and leading to the inhibition of cell proliferation." (PMID 35899119, 2022). "Patients with breast cancer who had low mRNA levels of FABP4, ADIPOQ, PPARG, and PPARGC1A had lower overall survival rates than those with high mRNA levels, which was supported by the overall survival related to DNA methylation." (PMID 36114448, 2022).
breast cancer (continued). "NR4A1 has been found to bind to the NBRE or coactivator SWI/SNF complex response elements by NR4A2 or PPARγ, resulting in the change of fatty acid-related genes ACOX, CPT1M, FABP2, and FABP4 in melanoma and breast cancer." (PMID 36052242, 2022). "Taken together, mammary tumor progression is enhanced by this macrophage subset, which is mechanistically accumulated in the tumor stroma through FABP4 mediated miR-29b/IL-6/STAT3 cascade." (PMID 36060264, 2022). "Emerging evidence suggests that elevated concentrations of FABP4 in the bloodstream are involved in breast cancer progression." (PMID 36060264, 2022). "In breast cancer metastasis and recurrence subsets, the expression of the FABP4 protein is downregulated, while the expression of other proteins is upregulated." (PMID 36532833, 2022). "The expression of FABP4 protein in 9 kinds of tumors including breast cancer, lung cancer, and colon cancer was lower than that in normal tissues, and there was statistical significance." (PMID 36532833, 2022). "A study by Kim showed that only a few patients with breast cancer express FABP4, including luminal A (0.8%), luminal B (0.7%), HER2+ (6%), and TNBC (4%)." (PMID 36114448, 2022). "A previous study found that FABP4 was upregulated in recurrent human breast cancer samples; FABP4 protects cancer cells from oxidative stress-induced ferroptosis and is associated with a worse prognosis in cancer patients." (PMID 36407322, 2022). "Recently published studies have also confirmed FABP4 expression in cancer cells, like breast cancer, ovarian cancer, colon cancer and so on." (PMID 36060264, 2022). "Then, in ROC analysis, we calculated AUC and found that FABP4 has a high value in the diagnosis of gastric cancer, colorectal cancer, breast cancer, and thyroid cancer." (PMID 36532833, 2022). "Further, evidence has also shown that fatty acid-binding protein 4 (FABP-4) is also found to be increased in breast cancer cells and is responsible for the intracellular trafficking of fatty acids." (PMID 35269622, 2022). "Meanwhile, disease-free survival (DFS) was found to be significantly correlated with FABP4 expression in breast cancer (p = 0.049)." (PMID 36532833, 2022). "Patients with breast cancer who had low mRNA expression levels of FABP4 (log-rank P = 0.012), ADIPOQ (log-rank P = 0.01), and PPARG (log-rank P = 0.00013) had worse OS than those with high mRNA levels." (PMID 36114448, 2022). "In breast cancer, FABP4 expression was highest in the HER2 subtype and lowest in the luminal A subtype, and HER2 overexpression-mediated oncogenic transformation of breast cells was accompanied by increased FABP4 expression." (PMID 36498537, 2022). "Concretely, Adipocytes promoted breast cancer growth through mitochondrial β-oxidation by using fatty acid from adipocytes, of which process fatty-acid-binding protein 4 (FABP4) was a key activated target for metabolic interaction." (PMID 35701840, 2022). "FABP4 has been found to promote the progression of ovarian cancer, cervical cancer, breast cancer, prostate cancer cell carcinoma, and oral squamous cell carcinoma." (PMID 36338624, 2022). "Inhibition of CD36 and FABP4 induces apoptosis in breast cancer cells and inhibits the growth of mouse xenografts." (PMID 36532833, 2022). "The area under the curve (AUC) of FABP4 is 0.931 for colorectal cancer, 0.960 for breast cancer, 0.985 for lung cancer, 0.956 for thyroid cancer, and 0.898 for gastric cancer, which has a high diagnostic value." (PMID 36532833, 2022). "Focusing on the mechanisms in breast cancer progression, FABP4 enhances proliferation in both MCF-7 cells (ER-positive) and MDA-MB-231 TNBC cells but does not appear to affect the migration potential." (PMID 34944905, 2021). "Of particular interest, circulating blood concentration FABP4 levels have been proposed as a new independent breast cancer biomarker as it was found increased in breast cancer patients." (PMID 33801973, 2021).
breast cancer (continued). "In this study, we demonstrated that FABP4 activity is required for breast cancer cell survival in nutrient deprivation conditions, both in control conditions and in co-culture with adipocytes." (PMID 34359819, 2021). "FABP4 supplementation increases tumor volume, tumor-initiating frequency and stemness markers, as shown in in vivo and in vitro studies on mammary tumors, depending on the IL-6/STAT3/ALDH1 signaling pathway." (PMID 34202411, 2021). "Serum fatty acid binding protein-4 (FABP4) has been reported as higher in obese compared to lean breast cancer survivors and is thought to play a role in breast cancer progression by facilitating provision of fatty acids to cancer cells." (PMID 34638355, 2021). "FABP4-positive TAMs accumulate in late-stage mammary tumours, promoting their growth through the enhancing effect FABP4 has on NF-κB expression, thereby increasing the secretion of pro-tumour IL-6 signalling." (PMID 34572888, 2021). "We also found that breast cancer cells induce the transcription of different fatty acid transporters such as FABP4, FABP5 and CD36." (PMID 34884983, 2021). "Circulating levels of FABP4 are markedly increased in obese individuals due to release from an expanded adipose tissue depot and FABP4 can induce mammary tumor stem cells by enhancing ALDH1 activity via IL-6/STAT3 signaling." (PMID 33339340, 2020). "When breast cancer cells are cultured with adipocytes in a cell line study, lipid droplets accumulate within cancer cells, and expression levels of FABP4, CD36 and perilipin 2, molecules that play roles in lipid transfer, are increased." (PMID 32674405, 2020). "We created a “fatty acid metabolism gene signature” consisting of CD36, LPL, PDK4, and FABP4 and checked each molecular subtype of breast cancer for upregulation or amplification of these genes." (PMID 31942031, 2020). "Similar to CD36, PDK4 and FABP4 are also highly expressed in CL breast cancers compared to all other molecular subtypes with the exception of normal-like breast tumours." (PMID 31942031, 2020). "It has been demonstrated that FABP4 was up-regulated in most tumors, such as prostate cancer and breast cancer." (PMID 33088219, 2020). "In prostate and breast cancer, the mRNA and protein levels of FABP4 expression were also significantly up-regulated." (PMID 33088219, 2020). "The fatty acid binding protein 4 (FABP4), which is an adipokine for fatty acid transport increases breast cancer cell proliferation and promotes expression of fatty acid transporters such as CD36 and FABP5." (PMID 31817676, 2019). "The function of FABP4 has been observed in various cancers, including non‐small cell lung cancer, breast cancer, bladder cancer, ovarian cancer, and prostatic cancer 12, 13, 14, 15, 16, 17, however, its role in HCC remained unclear." (PMID 29733540, 2018). "The role of FABP4 has been reported in various cancers, such as non‐small cell lung cancer, breast cancer, ovarian cancer, and prostatic cancer." (PMID 29733540, 2018). "Loss of expression of FABP4 was reported in bladder cancer while FABP1 and FABP2 are over-expressed in prostate and breast cancers." (PMID 18826602, 2008). "It is of great interest to understand whether and how FABP4 and FABP5 link dysregulated lipid metabolism to breast cancer risk and progression." (PMID 40106183, 2025). "Interestingly, in breast cancer tissue, we further observed that FABP4 remains primarily expressed in stromal adipocytes, endothelial cells and macrophages, whereas FABP5 is significantly upregulated in epithelial-derived tumor cells." (PMID 40106183, 2025). "For example, breast cancer-associated fibroblasts (CAFs) promote lipid take up in tumor cells through the FABP2/FABP3 pathway, and ovarian cancer cells uptake fatty acids released by adipocytes through FABP4 to support metastasis." (PMID 40717587, 2025).
breast cancer (continued). "For example, FABP1 enhances mitochondrial β-oxidation in hepatocellular carcinoma to provide energy, while FABP4 promotes breast cancer cells to take up fatty acids from adipocytes and activates the STAT3 pathway to drive epithelial-mesenchymal transition (EMT)." (PMID 40717587, 2025). "Given that FABP4 is typically elevated in breast cancer, this finding raises the possibility that circulating FABP4 could potentially serve as a specific marker for lymphedema after cancer remission." (PMID 40759794, 2025). "In addition, exogenous FABP4 played a vital role in breast cancer progression and regulated fatty acid transport proteins expression." (PMID 40963862, 2025). "To dissect the potential role of FABP4 in breast cancer development and progression, we first analyzed the correlation of FABP4 expression in tumor cells with various clinical parameters, including age, BMI, tumor size, Elston-Ellis grade, metastasis, and patient vital status." (PMID 40106183, 2025). "Moreover, intracellular levels of FABP4 in MCF-7 and MDA-MB-231 breast cancer cell lines increased after exogenous FABP4 incubation, which enhanced their proliferation rate." (PMID 39941898, 2025). "In our study, we found that plasma FABP4 levels in breast cancer-related lymphedema patients remained elevated in individuals who no longer had active cancer, similar to the high circulating FABP4 levels reported in studies evaluating breast cancer patients before initiating cancer treatments." (PMID 40759794, 2025). "Further investigation into the dynamics of specific FABPs, such as FABP5 and FABP4, and their differential expression in distinct stages of breast cancer could unveil nuanced regulatory mechanisms that impact TAM behavior." (PMID 38411356, 2024). "Given emerging roles of dysregulated lipid metabolism in cancer growth and metastasis, blocking FABP4 activity represents a novel strategy for breast cancer treatment as it blocks lipid transportation and metabolism, thus inhibiting cancer cell growth and metastasis." (PMID 39054536, 2024). "Furthermore, FABP4 enhances lipolysis and FA utilization by breast cancer cell lines, which promotes cancer cell migration in vitro and metastasis in vivo." (PMID 39513934, 2024). "Moreover, triple negative breast cancer exhibited higher FABP4 expression in macrophages than ER+ or HER2+ breast cancer." (PMID 39513934, 2024). "Moreover, FABP4 deficiency impaired LA-mediated protumor migration effect of macrophages, further supporting that FABP4-mediated lipolysis in macrophages was critical for lipid utilization by breast cancer cells." (PMID 39513934, 2024). "Mechanistically, SCD1 catalyzes fatty acid desaturation and synergistically promotes lipid droplet formation with FABP4 in the breast cancer microenvironment, alleviating hypoxia-induced ferroptosis in MDA-MB-231 cells and promoting cancer cell regeneration and recurrence." (PMID 39664391, 2024). "(H) Analysis of FABP4 expression levels between alive and deceased breast cancer patients." (PMID 39513934, 2024). "However, during the late stages of breast cancer progression, macrophages exhibit high FABP4 expression, which facilitates IL‐6/STAT3 signaling and promotes the anti‐inflammatory phenotype of macrophages." (PMID 38411356, 2024). "Blocking circulating FABP4 with monoclonal antibodies might represent a novel therapeutic strategy for treatment of breast cancer." (PMID 39054536, 2024). "We also observed reduced expression of LIPE and FABP4 genes in CAAs in comparison to adipocytes, which was also described in types of cancer (such as breast cancer) and might seem to be inconsequential." (PMID 37316878, 2023). "Furthermore, there is clinical significance of SCD1 and FABP4 expression in primary human tumors and metastatic tissues that relapse after first-line chemo- or hormone therapy in breast cancer patients." (PMID 38060103, 2023).